EGFR (epidermal growth factor receptor)
Diseases named in the same sentence as EGFR in open-access papers (continued):
Sharing a sentence is not in itself a finding about the gene and the disease.
breast carcinoma (continued). "When EGFR-overexpressing MDA-MB-231-BR brain-seeking breast cancer cells were injected into a mouse model, lapatinib reduced metastatic colonization in mouse to 50–53%." (PMID 27738326, 2016). "A portion of ERα-positive breast cancers also express EGFR (see review by Osborne and Schiff and references therein)." (PMID 27129152, 2016). "Mutations of epidermal growth factor receptor (EGFR) have been found in several tumor entities including gliomas, breast cancer, and non-small lung cancer." (PMID 27409604, 2016). "Combination treatment with irreversible EGFR TKIs and ethacrynic acid (EA) had a synergistic antitumor effect in breast cancer cells." (PMID 27487128, 2016). "Our findings advance the current understanding of anti-EGFR immunotherapy failures in breast cancer." (PMID 27462789, 2016). "Platycodin D which is an active triterpenoid saponin from Platycodon grandiflorum inhibited migration, invasion, and growth of MDA-MB-231 human breast cancer cells via suppression of EGFR-mediated Akt and MAPK pathways." (PMID 26636541, 2016). "Exosomes loaded with let-7a miRNA were intravenously administrated to EGFR-expressing breast cancer mouse model, resulting in significant inhibition of tumor growth." (PMID 27187371, 2016). "We validated this in EGFR overexpressing SK-BR-3 breast cancer cells, where miR-644a overexpression significantly sensitized cells to gefitinib." (PMID 27409664, 2016). "As a dual tyrosine kinase inhibitor against both EGFR and erbB2, lapatinib has been approved to treat the erbB2-positive breast cancer patients that have progressed on trastuzumab-based regimens." (PMID 26621843, 2016). "In the present study, we found that DCA sensitized MCF7 breast cancer cells to tamoxifen-induced cell death by decreasing epidermal growth factor receptor (EGFR) expression." (PMID 27494858, 2016). "Some studies revealed that EGCG is able to inhibit the activation of HER2 and EGFR in different cancer cells lines, such as, lung, thyroid, breast cancer and squamous-cell carcinoma." (PMID 27213442, 2016). "Accordingly, it is important to develop new breast cancer therapies based on the combination of Hh pathway inhibitors and ErbB2, EGFR, Wnt and Notch signaling inhibitors." (PMID 26843616, 2016). "Here, we demonstrated that DCA inhibits not only PDK activity but also EGFR expression in breast cancer cells." (PMID 27494858, 2016). "In the dataset, perturbations (i.e., inhibitor of EGFR or stimuli of DNA damage or both) were applied to cells of the breast cancer cell line BT20." (PMID 26818802, 2016). "Our findings support evidence demonstrating that growth factor receptors, such as insulin-like growth factor receptor (IGF-1R), EGFR, and ErbB2, play critical roles in the mediation of endocrine resistance in breast cancer." (PMID 27659519, 2016). "EGFR neutralizing antibody cetuximab restores trastuzumab sensitivity of breast cancer BT474-T798M cells and xenografts, suggesting that increased EGFR ligand production was causally associated with trastuzumab resistance." (PMID 26863629, 2016). "For immunofluorescence microscopy, we used MTLn3 breast cancer cells as an in vivo model of EGFR-mediated trafficking, as these breast cancer cells contain upwards of ~5 × 104 EGF receptors per cell." (PMID 27256981, 2016). "Clinical studies have indicated an increased expression of Epidermal Growth Factor Receptor (EGFR/ERRB1) and its family member ERBB2 in breast cancers which are associated to tumor development, progression." (PMID 27564112, 2016). "Taken together, our findings suggest that a combination of E1A gene therapy or an AXL inhibitor and EGFR-TKI will improve treatment of breast cancer." (PMID 27590506, 2016). "CDCP1 and EGFR cooperate to induce detachment of breast cancer cells from the substratum and to disrupt adherens junctions." (PMID 27495374, 2016). "In the present study, we demonstrated that the expression of EGFR in breast cancer cells was decreased by treatment with DCA." (PMID 27494858, 2016).
breast carcinoma (continued). "Prolonged treatment of breast cancer with epidermal growth factor receptor (EGFR) tyrosine kinase inhibitors (TKIs) often results in acquired resistance and a narrow therapeutic index." (PMID 27487128, 2016). "EGFR is highly expressed in various cancers and involved in cell proliferation, migration, and viability during the process of various cancers, such as breast cancer." (PMID 27465833, 2016). "The blocked Anxa 2 or the Anxa 2 knockdown inhibits the activation of the EGFR downstream pathways and reduces breast cancer cell migration." (PMID 27274723, 2016). "EGFR regulates mammary gland development and in certain aggressive breast cancer cells has been shown to regulate invasion and migration." (PMID 27253373, 2016). "MiR-7 down-regulates expression of KLF4 in breast cancer stem cells and suppresses EGFR mRNA in several cancers by binding to sites in its 3′-UTR." (PMID 26840086, 2016). "Breast cancer cell lines were engineered to stably express EGFR, CDCP1 or phosphorylation site mutants of CDCP1." (PMID 27495374, 2016). "EGFR and cMET cross-talk is involved in breast cancer (BC) progression and resistance to different targeted therapies, however little is known about the co-expression patterns of EGFR and cMET or its prognostic significance in BC." (PMID 27055285, 2016). "The combined treatment of DCA and tamoxifen induced proteasome-dependent degradation of EGFR proteins in breast cancer cells via p38 MAPK activation." (PMID 27494858, 2016). "In this study, we found that downregulation of EGFR in DCA-treated breast cancer cells enhanced the sensitivity of the cells to tamoxifen." (PMID 27494858, 2016). "Recently, we have shown that NBD compounds bind to the extracellular region of EGFR and enhance tyrosine phosphorylation of EGFR, leading to aberrant triggering of downstream and lateral signaling in breast cancer and non-small lung cancer cells." (PMID 26883293, 2016). "Inhibition of EGFR was considered a potential therapeutic strategy for breast cancer patients because EGFR is commonly overexpressed in approximately 30% of breast cancers." (PMID 27590506, 2016). "Although the breast cancer cell lines used in our experiments express wild-type EGFR, each expresses this to a different degree." (PMID 27050072, 2016). "Non-small-cell lung cancer (NSCLC), oral squamous carcinoma, colorectal cancer, and breast cancer exhibits EGFR overexpression." (PMID 27051190, 2016). "Although most of these studies involved breast cancer with EGFR or ERBB2 overexpression, some researchers have conducted studies on the other HER family genes, including ERBB4." (PMID 26907936, 2016). "In this study, we investigated the effects of ethacrynic acid (EA) combined with irreversible EGFR TKIs on breast cancer both in vitro and in vivo." (PMID 27487128, 2016). "In this study, we found that inhibition of AXL (E1A gene therapy or R428) increases the sensitization of breast cancer cells to EGFR-TKI." (PMID 27590506, 2016). "The authors engineered the donor cells to express the transmembrane domain of platelet-derived growth factor receptor fused to the GE11 peptide in order to target EGFR positive breast cancer cells." (PMID 27187371, 2016). "To test this we treated a pair of LCLs along with their matching breast cancer cell lines with lapatinib, an epidermal growth factor receptor (EGFR) and HER2 tyrosine kinase inhibitor." (PMID 27224917, 2016). "Four genes from breast cancer stage III network pattern (KRT8, KRT17, KRT18 and HOXC10) physically interact with EGFR, a target gene of Lapatinib Breast cancer drug which is quite similar (greater than 50%) to Paroxetine (repurposed drug from LINCS)." (PMID 26892392, 2016). "In particular, the tumor suppressor miRNA let-7a has been efficiently delivered to epidermal growth factor receptor (EGFR)-expressing breast cancer cell, exerting the in vivo inhibition of tumor development." (PMID 27349385, 2016).
breast carcinoma (continued). "We next determined the effect of combination treatment with irreversible EGFR TKIs and EA on inhibiting the proliferation of breast cancer cells using CCK8 assays." (PMID 27487128, 2016). "For example, trastuzumab and gefitinib respectively target ERBB2 and EGFR from the same motif, and they have been used clinically in combination to treat breast cancer." (PMID 26853265, 2016). "Triple-negative breast cancer cells overexpress EGFR (epidermal growth factor receptor), but EGFR inhibitors are not clinically effective." (PMID 26828520, 2016). "Akin to FAM83A, the ability of FAM83B to promote aberrant signaling also correlates with resistance of breast cancer cells to EGFR TKI therapies." (PMID 27221039, 2016). "miR-7-5p suppresses the growth and metastasis of several tumor types, including hepatocellular carcinoma, breast cancer, glioma and gastric cancer, by inhibiting the expression of specific target genes, including EGFR and its signaling pathways." (PMID 27203220, 2016). "It had been demonstrated that overexpression of versican by G3 domain-containing EGF-like motifs enhanced breast cancer self-renewal through EGFR/AKT/GSK3β signaling, and increased resistance to chemotherapy." (PMID 27490467, 2016). "MDA-MB-231 cells have lower levels of EGFR in comparison to some breast cancer cell lines which leads to the ineffectiveness of EGFR inhibitors and EGFR function blocking antibody." (PMID 27203208, 2016). "Patterns of correlation between EGFR and cMET expression and phosphorylation in all breast cancers and subtypes." (PMID 27055285, 2016). "Other carcinomas with fewer patients (n = 2–5) also showed high percentage of EGFR/NeuGcGM3 positive cells: prostate, ovarian, cervical, breast carcinoma and glioblastoma multiform." (PMID 27449755, 2016). "Abnormally activated ErbB Family receptors (EGFR [ErbB1], HER2 [ErbB2], ErbB3 and ErbB4) and estrogen receptors (ER) are frequently implicated in breast cancer, making these potential therapeutic targets." (PMID 26835225, 2016). "We report that Pten-loss driven mammary tumors exhibit elevated PI3K pathway activity and reduced EGFR activity compared to PIK3CA mutant tumors." (PMID 26814435, 2016). "FDG uptake has furthermore been used to evaluate patients with HER2 positive breast cancer, which were treated with lapatinib, a clinically approved inhibitor of EGFR as well as HER2." (PMID 26460961, 2015). "In breast cancer cells and xenograft breast cancer models, methylation of EGFR by PRMT5 promotes breast cancer cellular proliferation and tumour progression through activation of the ERK-mediated oncogenic pathway." (PMID 26420673, 2015). "Anxa2 was highly expressed in all the EGFR positive breast cancer cell lines, and strongly positive expression of Anxa2 was found in cell lines that were characterized as mesenchymal-like and highly aggressive, such as MDA-MB-231, MDA-MB-435 and MCF-7/ADR." (PMID 26307676, 2015). "Other studies showed that exosomes can efficiently deliver miRNA to epidermal growth factor receptor-expressing breast cancer cells." (PMID 26248080, 2015). "One of the main objectives of this study is to determine the core regulators of EGFR signaling in breast cancer cells and understand their role in breast cancer." (PMID 26763900, 2015). "For different cancer cells, individualized targets are chosen according to the expression of antigens, such as transferring, Her-2, and epidermal growth factor receptor (EGFR) in breast cancer and EGFR in oral and epidermal cancers." (PMID 26339222, 2015). "This study describes a pro-metastatic EGFR/Src-dependent β4 integrin/FAK complex that is involved in breast cancer malignancy and is a novel therapeutic target for triple-negative breast cancer." (PMID 26549523, 2015). "In fact, it is reported that GEP100, a GEF for Arf6, links EGF/EGFR signaling to Arf6 activation to induce invasive activities of breast cancer cells." (PMID 25779663, 2015).
breast carcinoma (continued). "While only in a single breast cancer cell line, we demonstrate the potential for progesterone to activate EGFR signalling, consistent with progesterone potentiation of EGF responses in ZR-75-1 cells." (PMID 26498662, 2015). "In breast cancers treated with EGFR inhibitors, IGF1R can replace EGFR in heterodimers to confer resistance." (PMID 25629162, 2015). "In both oral squamous cell carcinoma and breast carcinoma cells, pharmacological inhibition of EGFR resulted in decreased expression of IMP3." (PMID 25886367, 2015). "Another agent, (+)-aeroplysinin-1 (a natural metabolite from a type of marine sponge), abolished the proliferative effect of EGF on breast cancer cells and inhibited the ligand-induced endocytosis of the EGFR in vitro." (PMID 26258011, 2015). "While there have been numerous studies focusing on the consequences of EGFR activation in breast cancer, less is known regarding the specific mechanisms through which the different EGF ligands promote early breast cancer growth and progression." (PMID 26215578, 2015). "A potential mechanism of tumor resistance against RTK inhibitors was found in non small-cell lung cancer (NSCLC) and HER2-positive breast cancer, where tumors became resistant to EGFR inhibition as a consequence of MET gene amplification." (PMID 26496080, 2015). "In breast cancer, EGFR is overexpressed in 20 ~ 50% of patients and plays a key role in promoting invasion." (PMID 26077136, 2015). "Exosomes from HEK293 cells stably expressing EGF or EGFR peptide have also been studied as therapeutic agents by targeting breast cancer cells expressing high levels of EGFR (such as the HCC70 breast carcinoma cell line)." (PMID 26601108, 2015). "Our results showed that PTPH1 disrupts the ER-EGFR complex through catalyzing EGFR tyrosine dephosphorylation leading to increased breast cancer sensitivities to TKIs." (PMID 26079946, 2015). "A previous study indicated that the fatty acid, oleic acid, activated EGFR signaling in breast cancer cells." (PMID 25679385, 2015). "EGFR-targeted therapy has had discouraging results in breast cancer treatment studies that include all subtypes of breast cancer." (PMID 25887413, 2015). "Another study in breast cancer epithelial cells found that EGFR is repressed by binding of the TIEG1/HDAC1 complex to SP1 sites on the EGFR promoter resulting in suppression of histone acetylation." (PMID 26243279, 2015). "One possible explanation for the macroscopically measured increase in EGFR dimer formation in response to gefitinib treatment is the prolonged duration of homodimerization events in live breast cancer cells after pretreatment with gefitinib." (PMID 25762314, 2015). "Substance P (SP) is a pleiotropic cytokine/neuropeptide that enhances breast cancer (BC) aggressiveness by transactivating tyrosine kinase receptors like EGFR and HER2." (PMID 26114632, 2015). "In glioblastoma, lung and breast cancer cells miR-7 blocked EGFR expression by means of accelerating mRNA decay." (PMID 26287249, 2015). "EGFR is overexpressed in breast cancer and is one of the first identified molecular targets for therapeutic intervention." (PMID 26079946, 2015). "This suggests that oncogenic PTPH1 in breast cancer is a physiologically important mechanism to counteract the growth-inhibitory signal of p-EGFR/Y1173 and the intrinsic resistance to TKIs." (PMID 26079946, 2015). "Curcumin was shown to inhibit functional interaction between integrin α6β4 and growth factor receptor, EGFR, a key event in breast carcinoma cell motility and invasion." (PMID 25665066, 2015). "In breast cancer, a dinucleotide CA-repeat within the first intron of the epidermal growth factor receptor (EGFR) gene correlates with the gene’s transcription levels." (PMID 26376692, 2015).
breast carcinoma (continued). "Human epidermal growth factor receptor 2 (HER2), a member of the epidermal growth factor receptor (EGFR) family, is overexpressed in approximately 20–30 % of human breast cancers, and its expression is associated with poor patient prognosis." (PMID 26285572, 2015). "EGFR signaling has been implicated in tamoxifenresistance in preclinical models, which could have significant implications for treatment, and lends further credence for EGFR pathway overexpression contributing to worse clinical outcomes in ER+ preM breast cancers." (PMID 26251034, 2015). "For example, ERp57 protein, a member of the disulfide isomerase family, participates in the activation of EGFR signaling and in the modulation of its internalization leading to enhanced breast cancer cell proliferation." (PMID 26258011, 2015). "Total PCBs associated with AREG, CYP19A1, ESR2, FOS, KRAS and STC2 genes; PCB 126 associated with AREG, CYP19A1, and STC2 genes and PCB 15 associated with CYP19A1, EGFR, ESR2, FOS, and IGF1 genes overlapped with 17β-estradiol, breast cancer, and endometriosis." (PMID 26512648, 2015). "Recent studies have also reported that activation of AXL is involved in the development of EGFR inhibitor resistance in breast cancer cells." (PMID 26356563, 2015). "Upregulation of HER3 has been found as one of the major mechanisms underlying drug resistance to EGFR and HER2 tyrosine kinase inhibitors (for example lapatinib, gefitinib, erlotinib) and to endocrine therapy in the treatment of breast cancer." (PMID 25849870, 2015). "However, EGFR mutations have also been found in 1/12 brain metastases from breast and 3/9 metastases from other primary cancers, suggesting that activation of the EGFR pathway may play a role in the metastatic development of breast cancer." (PMID 25969993, 2015). "For this purpose, non-permeabilized and permeabilized cells were stained for TRAIL-R2 and CXCR4, along with epidermal growth factor receptor (EGFR), frequently expressed at high levels in metastatic breast cancer cells, and TRAIL-R1." (PMID 25909161, 2015). "Our results however showed that PTPH1 decreases EGFR/Y1173 phosphorylation and increases breast cancer sensitivity to TKI-induced growth inhibition." (PMID 26079946, 2015). "While therapies targeting EGFR have been studied in breast cancer, these have focused predominately on triple-negative breast cancer, and there have not been previous studies specifically in ER+ patients." (PMID 26251034, 2015). "In many breast cancers, estrogen, progesterone and epidermal growth factor receptor-positive cells proliferate in response to growth factors and growth factor antagonists are a mainstay of treatment." (PMID 25678856, 2015). "Human breast cancer cells selected for resistance to trastuzumab in vivo overexpress epidermal growth factor receptor and ErbB ligands and remain dependent on the ErbB receptor network." (PMID 25879571, 2015). "These type-C inhibitors are able to maintain activities for drug-resistant EGFR and decrease the invasion ability of breast cancer cells." (PMID 26077136, 2015). "Since we observed a correlation between FABP5 and EGFR in breast cancer patient samples, we further analyzed the functional and mechanistic relationship between FABP5 and EGFR in TNBC cells." (PMID 25779666, 2015). "Our discovery of AMPK-mediated regulation of HER2 and EGFR signaling provides a novel mechanism to explain heightened sensitivity of HER2 and EGFR overexpressing breast cancer cell lines to the AMPK activating agent, AICAR." (PMID 26143491, 2015). "Upregulation of HER3 has been found to be a major mechanism underlying drug resistance to EGFR and HER2 tyrosine kinase inhibitors and to endocrine therapy in the treatment of breast cancer." (PMID 25849870, 2015). "EGFR overexpression was observed in most clinically aggressive subtypes of breast cancer, including triple-negative breast cancer and inflammatory breast cancer, and predicted poor prognosis in cancer patients." (PMID 26307676, 2015).